HLA-U (major histocompatibility complex, class I, U (pseudogene))
Synonyms: Em:AB023056.13; formerly HLA-21
Gene: Unprocessed pseudogene on chromosome 6 (29,934,101 to 29,934,286, forward strand). Ensembl gene ENSG00000228078.
Diseases named in the same sentence as HLA-U in open-access papers:
HLA-U is named in the same sentence as 3 diseases in open-access papers, as found by Europe PMC text mining. Sharing a sentence is not in itself a finding about the gene and the disease.
HLA-U shares sentences with these, for which no sentence is quoted: infection (2 papers); breast carcinoma (1); tumour (1).